CDC6 (cell division cycle 6)
Diseases named in the same sentence as CDC6 in open-access papers (continued):
Sharing a sentence is not in itself a finding about the gene and the disease.
glioma (13 papers, 2015 to 2024). A benign or malignant brain and spinal cord tumor that arises from glial cells (astrocytes, oligodendrocytes, ependymal cells). "For example, a study published in the journal Nature Communications found that CDC6 gene expression levels were significantly elevated in gliomas, and its overexpression was strongly associated with tumor malignancy and prognosis." (PMID 37342242, 2023). "As well as age, IDH status, 1p/19q coding status, WHO classification, poor overall survival (OS), and histological type of glioma, high CDC6 expression was significantly associated with poor OS." (PMID 37342242, 2023). "Meanwhile, high CDC6 expression was associated with poor overall survival (OS) in glioma patients, especially in different clinical subgroups." (PMID 35879762, 2022). "CDC6 has been reported to be associated with immune infiltration and is a potential prognostic biomarker in glioma." (PMID 36531013, 2022). "CDC6 is highly expressed in high-grade gliomas and was significantly associated with decreased patient survival." (PMID 33804958, 2021). "CDC6 promotes the proliferation, migration, and invasion of glioma cells and inhibits the apoptosis of these cells." (PMID 39684684, 2024). "CDC6 expression in glioma was positively correlated with Th2 cells, Macrophages and Eosinophils, and negatively correlated with plasmacytoid dendritic cells, CD8 T cells and NK CD56bright cells, suggesting its role in regulating tumor immunity." (PMID 36599883, 2023). "Recent studies have shown that the CDC6 gene plays an important role in a variety of tumors, including gliomas." (PMID 37342242, 2023). "CDC6 was highly expressed in patients with low-grade gliomas with short overall survival.CDC6 was highly expressed in gliomas and increased with increasing glioma grade." (PMID 37342242, 2023). "Glioma proliferation was inhibited by knocking down CDC6 in U87 glioma cells by means of small interfering RNA." (PMID 37342242, 2023). "In gliomas, CDC6 expression was positively related to Th2 cells, macrophages, and eosinophils and negatively related to plasmacytoid dendritic cells and CD8 T cells, and NK CD56 bright cells." (PMID 37342242, 2023). "We found that patients with unremitting gliomas in grade III and low-grade gliomas were highly expressed in CDC6 and had shorter survival after treatment (p<0.05)." (PMID 37342242, 2023). "Further, we evaluated the relationship between CDC6 expression and the prognosis of glioma patients." (PMID 37342242, 2023). "CDC6 expression was evaluated in a mouse subcutaneous glioma model, and it was found that the shCDC6 group did express decreased CDC6." (PMID 37342242, 2023). "We found that the protein levels of cyclin D1, CDK6 and CDC6 were reduced in UM-164-treated glioma cells in both dose- and time-dependent manners." (PMID 36358761, 2022). "In an effort to assess the expression levels of CDC6 in other radioresistant cancer types, we analyzed the correlations of CDC6 level and the tumor progression in the low-grade glioma with/o IR and chemotherapy." (PMID 30158672, 2019). "In gliomas, CDC6 expression is positively correlated with macrophage infiltration." (PMID 39684684, 2024). "Similarly, the high expression of CDC6 is significantly related to the survival rate and immune infiltration of gliomas." (PMID 39684684, 2024). "RNA-seq analysis showed that TSD-fed normal mouse serum could regulate CDC6 pathway activity in glioma cells." (PMID 37342242, 2023). "Finally, we plotted the ROC curve of CDC6 as an independent indicator to determine normal and glioma tissues." (PMID 37342242, 2023). "Multiple types of tumors, including gliomas, were shown to express higher levels of CDC6." (PMID 37342242, 2023).
glioma (continued). "We evaluated the clinical relevance of CDC6 in gliomas using data from the TCGA database." (PMID 37342242, 2023). "Then, Q-PCR confirmed that MCM 10 and CDC6 were high expressed in glioma cells of Control group." (PMID 37342242, 2023). "On this basis we evaluated whether glioma growth was restricted in the mouse in situ glioma model due to the low expression of CDC6." (PMID 37342242, 2023). "Moreover, high expression of CDC6 was significantly associated with age, IDH status, 1p/19q codeletion status, WHO grade and histological type in glioma (all p < 0.05)." (PMID 35879762, 2022). "Furthermore, we focused on the relationships between CDC6 expression, its prognostic value, potential biological functions, and immune infiltrates in glioma patients." (PMID 35879762, 2022). "Furthermore, a univariate Cox analysis showed that high CDC6 expression was correlated with poor OS in glioma patients." (PMID 35879762, 2022). "However, several studies have identified that the CDC6 gene may play a key role in the development and progression of gliomas." (PMID 37342242, 2023). "This suggests that the CDC6 gene may be a potential therapeutic target for gliomas." (PMID 37342242, 2023). "In addition, another study found that the growth and proliferation of glioma cells could be inhibited by interfering with the expression of the CDC6 gene." (PMID 37342242, 2023).
bladder cancer (10 papers, 2016 to 2026). "CDC6 has also been reported to be associated with cisplatin resistance by activation of ATR-Chk1 pathway in bladder cancer cells." (PMID 32792963, 2020). "Expression of CDC6 is increased in bladder cancer and its knockdown can attenuate cell migration and invasion in addition to increased sensitivity to cisplatin." (PMID 36997866, 2023). "We next examined Cdc6 protein expression in bladder cancer cell lines UMUC3, 5637, and T24 by Western blot." (PMID 27246979, 2016). "The results indicate that Cdc6 expression in high grade bladder cancer tissues is higher than that in low grade cancer tissues." (PMID 27246979, 2016). "Cdc6 depletion can attenuate the malignant properties of bladder cancer cells, including DNA replication, migration and invasion." (PMID 27246979, 2016). "In order to investigate Cdc6 expression profile in bladder urothelial carcinoma, the tumor samples as well as paired adjacent bladder tissues from 12 patients with primary bladder cancer were analyzed by Western blot." (PMID 27246979, 2016). "More importantly, Cdc6 promotes CDDP resistance in bladder cancer cells by collaborating with ATR signal pathway." (PMID 27246979, 2016). "In this paper, we showed that Cdc6 down-regulation by RNAi can attenuate the malignant properties of bladder cancer cells, including DNA replication, migration and invasion and more importantly, enhance sensitivity of both UMUC3 and UMUC3R cells to CDDP." (PMID 27246979, 2016). "Cdc6 is expressed ubiquitously in bladder cancer cell lines and the strongest Cdc6 expression was detected in UMUC3 cells." (PMID 27246979, 2016). "Here, we reported that Cdc6 expression is up-regulated in bladder cancer tissues and is positively correlated to high tumor grade." (PMID 27246979, 2016). "BrdU incorporation assays revealed that the percentage of BrdU-positive cells was decreased from 22% in control group to 14% in Cdc6 RNAi group in bladder cancer UMUC3 cells (P<0.05)." (PMID 27246979, 2016). "High expression of Cdc6 was found in 81 out of 115 bladder cancer patient (70.4%), significantly higher than in normal samples (6%, 3 in 50, P<0.05)." (PMID 27246979, 2016). "In conclusion, we report that Cdc6 is upregulated in bladder cancer tissues and is positively correlated with tumor grade and associated with poor disease free survival." (PMID 27246979, 2016). "Further studies showed that down-regulation of CDC6 expression in bladder cancer could significantly inhibit a variety of malignant phenotypes of tumor cells." (PMID 38519533, 2024). "Furthermore, OTUD6A protein level has a positive correlation with CDC6 protein level, and high protein levels of OTUD6A and CDC6 are associated with poor prognosis in patients with bladder cancer." (PMID 38685067, 2024). "What’s more, exosomal miR-93-5p suppressed BTG2 expression and promoted bladder cancer cells progression, exosomal EphA2 promoted the invasion and migration of bladder cancer cells, exosomal CDC6 effectively repressed the malignant process of bladder cancer cells." (PMID 37805491, 2023). "As high Cdc6 expression correlates with high tumor grade and poor disease free survival, we reasoned that Cdc6 may have an impact on migration and invasion in bladder cancer cells." (PMID 27246979, 2016). "Our results indicate that Cdc6 may be a promising target for overcoming CDDP resistance in bladder cancer." (PMID 27246979, 2016). "Besides, bladder cancer patients with Cdc6 up-regulation have significantly shorter disease free survival time than those with lower Cdc6 expression." (PMID 27246979, 2016). "We also investigated the role of Cdc6 on malignant properties in bladder cancer cell lines." (PMID 27246979, 2016). "We also compared Cdc6 expressions in high grade and low grade bladder cancer tissues (Figure 1A2)." (PMID 27246979, 2016).
bladder cancer (continued). "Recent research also found that down-regulated CDC6 expression in bladder cancer cells and exosomes could inhibit the malignant processes of bladder cancer cells, revealing that targeting this exosome-derived gene might be a promising treatment strategy against tumours." (PMID 38728235, 2024). "Therefore, we speculate that inhibition of Cdc6 may enhance the sensitivity of CDDP-resistant bladder cancer cells by disturbing the ATR checkpoint signal." (PMID 27246979, 2016). "Intriguingly, down-regulation of Cdc6 can enhance sensitivity to CDDP both in bladder cancer cells and CDDP-resistant bladder cancer cells." (PMID 27246979, 2016). "In this research, CDDP-resistant bladder cancer cells shows increased chromatin-binding ATR and Cdc6 compared to parent cells." (PMID 27246979, 2016). "In addition, TACC3 is highly co-expressed with MCM4, CDC6, and CDC25A, indicated by correlation analysis using RNA-seq data of 42 bladder cancer clinical samples from our group published before." (PMID 29358577, 2018). "Considering the deficiency of G1 phase checkpoint in cancer cells and the important roles of Cdc6 and ATR in chemo-resistant cancer cells, Cdc6 may be a potential specific therapeutic target for bladder cancer, especially for CDDP-resistant bladder cancer." (PMID 27246979, 2016). "Furthermore, higher levels of chromatin-binding Cdc6 and ATR were detected in CDDP-resistant bladder cancer cells than in the parent bladder cancer cells." (PMID 27246979, 2016). "Accordingly, inhibition of Cdc6 could enhance cytotoxicity of CDDP in both parent and CDDP-resistant bladder cancer cells." (PMID 27246979, 2016).
colorectal cancer (10 papers, 2020 to 2025). A primary or metastatic malignant neoplasm that affects the colon or rectum. "HCT116 colorectal cancer cells were sensitive to the suppression of CDC6, the protein involved in the recruitment of the MCM complex to the origin of replication." (PMID 32612138, 2020). "Furthermore, HuR enhanced the resistance of colorectal cancer to oxaliplatin by upregulating the expression of CDC6." (PMID 40853971, 2025). "However, a previous study found that the five-year survival rate of the CDC6 high-expression group was lower than that of the low-expression group in colorectal cancer." (PMID 39684684, 2024). "According to EpiFactor, the CDC6 and ORC1 genes significantly induce epigenetic modifications affecting gene expression in colorectal cancer." (PMID 37945594, 2023). "Colorectal samples in the TCGA cohort were grouped into high-expressed and low-expressed samples based on the median of CDC6 and ORC1 expression, and the Tide algorithm was conducted to investigate immunotherapy response in colorectal cancer samples." (PMID 37945594, 2023). "Chromatin remodeling or acetylation in CDC6/ORC1 may delay DNA replication and promote the development of colorectal cancer." (PMID 39963131, 2025).
ovarian carcinoma (10 papers, 2012 to 2025). A malignant neoplasm originating from the surface ovarian epithelium. "Transfection of CDC6 siRNA leads to not only decreased level of ovarian cancer cell proliferation but also increased apoptosis rates." (PMID 34249670, 2021). "High expression of CDC6 in epithelial ovarian cancer (EOC) cells was indicated as a new potential therapeutic target for EOC patients." (PMID 28969025, 2017). "As an example, miR-26a was first shown to promote ovarian cancer proliferation through its suppression of ER-α, while subsequently, it was shown to inhibit proliferation of ovarian cancer cells through its regulation of CDC6." (PMID 33802524, 2021). "The expression level of CDC6 in ovarian cancer tissues was significantly higher than that in adjacent tissues and it was related to tumor stage, differentiation degree, lymph node metastasis, ascites and prognosis, which was an independent factor of ovarian cancer patients." (PMID 38519533, 2024).
Meier-Gorlin syndrome (8 papers, 2012 to 2024). "Recessive mutation of CDC6 is associated with Meier-Gorlin syndrome (MGS), a rare congenital anomaly syndrome characterized by impaired pre- and postnatal growth, short stature, microcephaly, microtia and absent or small patellae." (PMID 38685067, 2024). "Core ORC components, such as CDC6, are mutated in Meier-Gorlin syndrome which features a variety of skeletal defects including scoliosis." (PMID 37100808, 2023). "Mutations in ORC1, ORC4, ORC6, CDT1, and CDC6, which encode proteins required for DNA replication origin licensing, cause Meier-Gorlin syndrome (MGS), a disorder conferring microcephaly, primordial dwarfism, underdeveloped ears, and skeletal abnormalities." (PMID 23516378, 2013). "Recently, mutations in genes encoding ORC1, ORC4, ORC6, CDT1, and CDC6 were identified in patients displaying Seckel syndrome (SS) and/or Meier-Gorlin syndrome (MGS)." (PMID 23516378, 2013). "Importantly, similar to Meier-Gorlin syndrome in humans, which can be caused by CDC6 mutation, depletion of OTUD6A in mice causes postnatal growth retardation, suggesting that OTUD6A is required for normal development at least partially through maintenance of CDC6 protein stability." (PMID 38685067, 2024). "A form of dwarfism known as Meier-Gorlin syndrome (MGS) is caused by recessive mutations in one of six different genes (ORC1, ORC4, ORC6, CDC6, CDT1, and MCM5)." (PMID 29036220, 2017). "Meier-Gorlin syndrome (MGS) is caused by mutations in components of the prereplication and pre-initiation DNA replication complexes (ORC1, ORC4, ORC6, CDT1, CDC6, GMNN, CDC45), which license replication origins and mediate loading and functioning of the replication fork helicase." (PMID 28630177, 2017).
non-small cell lung carcinoma (8 papers, 2009 to 2025). A group of at least three distinct histological types of lung cancer, including non-small cell squamous cell carcinoma, adenocarcinoma, and large cell carcinoma. "High levels of Cdc6 have been reported in around 50% of non-small cell lung carcinomas, brain cancer and a subset of mantle cell lymphomas, which suggests that Cdc6 has oncogenic properties." (PMID 27861149, 2017). "Expression of CDC6 in non-small cell lung cancer cells, as assessed with RT-PCR, partitions cells into two groups; one with baseline expression, and a second group with highly elevated expression." (PMID 19619298, 2009). "As an example, in early- to mid-stage non-small cell lung cancer, Claspin was only one of a set of five genes (POLQ, PLK1, RAD51, CDC6, and CLSPN) encoding proteins involved in the maintenance of genome stability that were found to be consistently upregulated and associated with poor survival." (PMID 41009395, 2025). "CDC6 is also overexpressed in 50% of cases of non-small cell lung cancer and mantle cell lymphoma." (PMID 26317630, 2015). "In non-small cell lung cancer, POLQ upregulates DNA replication initiation proteins such as CDC6 and PLK1, enhancing tumor cell tolerance to replication stress, promoting cell proliferation, and resulting in poor prognosis." (PMID 38270643, 2024). "In addition, over-expression of POLQ, PLK1, RAD51, CDC6, and CLSPN was found to correlate with worse prognosis in non-small cell lung cancer." (PMID 41009395, 2025).
osteosarcoma (8 papers, 2011 to 2023). A usually aggressive malignant bone-forming mesenchymal neoplasm, predominantly affecting adolescents and young adults. "This difference in results indicates that the inhibition of cell proliferation occurs due to the deficiency of Cdc6 in PC cells and osteosarcoma but the mechanisms underlying these effects are different." (PMID 33020506, 2020). "However, in osteosarcoma cells, G1 cell cycle arrest was observed, and the expression of cyclin D1 and cyclin A2 was decreased due to Cdc6 deficiency." (PMID 33020506, 2020). "It has been demonstrated that downregulating CDC6 prevents osteosarcoma carcinogenesis in both in vivo and in vitro." (PMID 37594635, 2023). "It is well established that the CSN interacts physically with the APC/C and regulates several targets including Cyclin A and Cdc6 in human U2OS osteosarcoma cells." (PMID 21991377, 2011). "Also, Cdc6 was reported to be highly expressed in osteosarcoma patients and osteosarcoma cell lines, and proliferation was inhibited in MG63 cells due to the deficiency of Cdc629." (PMID 33020506, 2020). "In another study, silencing CDC6 reduced CCNA2 expression and suppressed osteosarcoma cell proliferation and invasion." (PMID 33858425, 2021). "In the osteosarcoma dataset of TARGET database, although BAP1 expression was similar in osteosarcoma tissues from patients with different clinicopathologic characteristics, it was positively correlated with BRCA1, CDC6, and CDC45." (PMID 36003792, 2022). "Consistent with the mouse 45Ca osteosarcoma cell lines, cilia frequency and expression of CDK1, CCNE1 and CDC6 did not correlate with CDKN2A deletion." (PMID 37845394, 2023).
gastric cancer (6 papers, 2020 to 2024). A primary or metastatic malignant neoplasm involving the stomach. "To understand the mechanism underlying the cell cycle arrest of gastric cancer cells induced by knocking down AURKB, we next examined the effect of AURKB on various key cell cycle regulatory molecules, including CCND1, CDC16, CDC6, CDC26, CCNB2, CCNF, p27 and E2F1, in gastric cancer cells." (PMID 31982864, 2020).